NLRP3 (NLR family pyrin domain containing 3)
Diseases named in the same sentence as NLRP3 in open-access papers (continued):
Sharing a sentence is not in itself a finding about the gene and the disease.
rectal cancer (2 papers, 2023 to 2025). A primary or metastatic malignant neoplasm that affects the rectum. "Eighteen studies highlighted the potential pathways of NLRP3 complex regulation as well as its role in the metastatic process in colo-rectal cancer, with promising results." (PMID 36834883, 2023). "We analyzed the correlation between NLRP3 expression and EMT-related genes in colon and rectal cancer tissues from the TCGA database using the GEPIA data analysis platform." (PMID 39744485, 2025).
relapsing-remitting MS (2 papers, 2018 to 2023). "Previous study on blood samples of patients with relapsing-remitting MS confirmed that the RNA expression levels of NLRP3 and IL-1β are upregulated in the acute phase and that the NLRP3 inflammasome is positively correlated with the response to interferon-β therapy in these patients." (PMID 36765034, 2023).
Respiratory Syncytial Virus Infection (2 papers, 2012 to 2025). "Cytidine/Uridine Monophosphate Kinase 2 (CMPK2) is an activator of the NLRP3 inflammasome that is differentially expressed in response to SARS-CoV-2, influenza virus, rhinovirus, and respiratory syncytial virus infection." (PMID 40778772, 2025).
retinal detachment (2 papers, 2018 to 2019). An eye emergency condition which may lead to blindness if left untreated. "The probable mechanisms include integrin α5β1 stimulated NLRP3 inflammasome expression and mature IL-1β secretion, and then resulted in severe NV and significant leakage that caused total exudative retinal detachment." (PMID 29502235, 2018). "In support of this, a study involving a mouse retinal detachment model showed that photoreceptor cell death was reduced when IL-1β and CASP1 were inhibited, as well as in Nlrp3−/− mice with retinal detachment, also indicating a role for inflammasome activation in this disease." (PMID 31379825, 2019). "Our data indicate that inhibition of integrin α5β1 ameliorates VEGF-induced retinal detachment by suppressing NLRP3 inflammasome signaling in Tet/opsin/VEGF transgenic mice, which could be beneficial for the treatment of RNV diseases." (PMID 29502235, 2018). "All these data suggested that NLRP3 inflammasome participated in the RNV and retinal detachment process in Tet/opsin/VEGF mice." (PMID 29502235, 2018).
salmonellosis (2 papers, 2014 to 2023). Infections with bacteria of the genus salmonella. "recently showed that Nlrp3/Nlrc4 double knockout mice have a markedly increased susceptibility for invasive salmonellosis when compared to WT controls." (PMID 25115174, 2014). "Therefore, in addition to revealing a novel aspect of interactions between Salmonella and inflammasomes, this study might also provide a potential strategy against salmonellosis, by triggering robust NLRP3 inflammasome activation to induce adaptive cellular immune responses." (PMID 37155697, 2023).
sleep disorder (2 papers, 2022 to 2024). A change from the patient's baseline sleeping pattern, in the hours slept and/or an alteration/dysfunction in the stages of sleep. "NLRP3 inflammasome signaling is a characteristic of sleep disorders and AD pathophysiology." (PMID 38720773, 2024).
stress-related disorder (2 papers, 2020 to 2021). Stress-related disorders are mental health disorders that are a result of an atypical response to both short and long-term anxiety due to physical, mental, or emotional stress. "Our findings suggest an association between NLRP3 activation, neuroinflammation, and PSD protein loss in fear memory, providing a novel target for the treatment of trauma- and stress-related disorders, such as PTSD." (PMID 32635937, 2020).
thoracic aortic aneurysm (2 papers, 2020 to 2024). An aneurysm formed in the wall of the proximal portion of the descending aorta proceeding from the arch of the aorta. "Moreover, the genetic deletion of NLRP3 or pharmacological inhibition of NLRP3 inflammasome with glyburide reduced the rate of thoracic aortic aneurysm formation in mice induced by high-fat diet and angiotensin II (Ang II)." (PMID 38732221, 2024).
Thrombocytosis (2 papers, 2025 to 2026). Increased numbers of platelets in the peripheral blood. "We conclude that Nlrp3 deletion in hematopoietic cells impedes thrombocytosis and granulocytosis in JAK2V617F-induced murine MPN." (PMID 41298546, 2025).
Tinnitus (2 papers, 2023 to 2025). Tinnitus is an auditory perception that can be described as the experience of sound, in the ear or in the head, in the absence of external acoustic stimulation. "For example, there was a trend toward greater staining for KCNQ3, NLRP3, and CD68 and lower staining for PREX2 and APLN in the VS samples associated with tinnitus compared to those without tinnitus." (PMID 37048724, 2023).
trigeminal neuralgia (2 papers, 2022 to 2024). Trigeminal neuralgia is a nerve disorder that causes a stabbing or electric-shock-like pain in parts of the face. "Our study reveals that OTULIN significantly mitigates neuropathic pain and neuroinflammation in trigeminal neuralgia by activating autophagy and inhibiting the NLR family pyrin domain containing 3 inflammasome, highlighting its potential as a therapeutic target." (PMID 39169794, 2024).
uremia (2 papers, 2021 to 2023). A clinical syndrome associated with the retention of renal waste products or uremic toxins in the blood. "Individual DAMPs that can elicit the NLRP3 inflammasome response in skeletal muscle in uremia are only partially known." (PMID 37447158, 2023). "Despite the study about basal activity of the NLRP3 inflammasome in hemodialysis (HD) patients, little is known about its inducibility in the milieu of uremia." (PMID 33430226, 2021). "Decreasing the gut production (or increasing the removal) of circulating DAMPs in uremia and/or anti-inflammatory treatments that target the NLRP3 to IL-1 to IL-6 pathway of innate immunity may offer a new paradigm to treat CKD-related PEW and CVD." (PMID 37447158, 2023). "IS, which is implicated in cardiovascular disease, was able to activate NLRP3 in myotubes, suggesting that it may act as one of the circulating DAMPs in uremia." (PMID 37447158, 2023). "Decreasing the production or removing circulating DAMPs in uremia and anti-inflammatory treatments that target the NLRP3 to IL-1 to IL-6 pathway of innate immunity may offer a new paradigm to treat CKD-related PEW and CVD." (PMID 37447158, 2023).
vascular occlusion (2 papers, 2023 to 2024). "NLRP3 inflammasome activation has been shown to trigger platelet aggregation, thrombosis, vascular occlusion, and inflammation." (PMID 37180702, 2023).
visceral leishmaniasis (2 papers, 2025). A severe form of leishmaniasis characterized by irregular bouts of fever, substantial weight loss, swelling of the spleen and liver, and anemia (which may be serious). "Whether there are differences in the roles of NLRP3 cutaneous versus visceral leishmaniasis is an issue that remains to be resolved." (PMID 41451223, 2025).
Wilson disease (2 papers, 2021 to 2025). A very rare inherited multisystemic disease presenting non-specific neurological, hepatic, psychiatric or osseo-muscular manifestations due to excessive copper deposition in the body. "Recently, NLRP3 has been reported to cause copper-mediated neurotoxicity in animal models of Wilson disease." (PMID 41462995, 2025).
α-synucleinopathy (2 papers, 2021 to 2023). "Increasing evidence also supports the pathological role of NLRP3 inflammasome in neurodegeneration based on a mutual association with mitochondrial dysfunction, which correlates with neurodegeneration in parkinsonian rats with α-synucleinopathy." (PMID 36902058, 2023). "Collectively, these results indicate that MitoApo ameliorates the αSynagg-induced ERS and TXNIP/NLRP3 signaling axis in a cell culture model of α-synucleinopathy." (PMID 34276337, 2021). "Together, our results suggest that inhibition of ERS and its downstream signaling mediators TXNIP and NLRP3 might represent novel therapeutic avenues for ameliorating microglia-mediated neuroinflammation in PD and other synucleinopathies." (PMID 34276337, 2021). "Therefore, our studies unravel a previously unknown mechanism linking PKCδ, ERS, and the TXNIP/NLRP3 signaling axis to the microglial activation response in the context of α-synucleinopathy." (PMID 34276337, 2021).
acute pharyngitis (1 paper, 2021). An acute and painful inflammatory process that affects the pharynx. "The results indicated that S. oblata could alleviate ammonia-induced acute pharyngitis by inhibiting the activation of TLR4/NF-κB/MAPK and NLRP3 inflammasome signaling pathways." (PMID 34925529, 2021).
acute promyelocytic leukemia (1 paper, 2018). An aggressive form of acute myeloid leukemia (AML), characterized by arrest of leukocyte differentiation at the promyelocyte stage, due to a specific chromosomal translocation t(15;17) in myeloid cells. "Promyelocytic leukemia (PML) proteins, which fuse with retinoic acid receptor alpha and induce tumors such as acute promyelocytic leukemia, were shown to be down-regulated by arsenic trioxide, and PML proteins are tightly involved in NLRP3 inflammasome activation." (PMID 30209319, 2018).
adenomyosis (1 paper, 2024). The growth of endometrial tissue inside the muscular wall of the uterine corpus. "This review summarizes the signaling pathways and targets associated with the pathogenesis of adenomyosis, including CXCL/CXCR, NLRP3, NF-κB, TGF-β/smad, VEGF, Hippo/YAP, PI3K/Akt/mTOR, JAK/STAT, and other relevant pathways." (PMID 39595579, 2024). "The study reported elevated expression of NLRP3 inflammasome components in both ectopic and eutopic endometrial tissues of patients with adenomyosis." (PMID 39595579, 2024). "A recent article has explored the potential of NLRP3 as a therapeutic target for adenomyosis." (PMID 39595579, 2024). "Furthermore, the use of an NLRP3 inhibitor in a mouse model of adenomyosis resulted in reduced migration and invasion of endometrial cells, contributing to the alleviation of the disease." (PMID 39595579, 2024). "Thus, targeting NLRP3 to inhibit the activation of the NLRP3 inflammasome may represent a promising therapeutic strategy for the management of adenomyosis." (PMID 39595579, 2024). "In the inflammatory disease adenomyosis, downregulation of the apoptosis-related gene 19 (GRIM19) activates the NLRP3 signaling pathway, leading to macrophage pyroptosis and increased secretion of IL-1β." (PMID 39595579, 2024).
adenosquamous carcinoma (1 paper, 2021). A carcinoma composed of malignant glandular cells and malignant squamous cells. "In addition, ACG treatment remarkably down-regulated the expression of TLR4, p-P65, NLRP3, Caspase-1 and adenosquamous carcinoma (ASC) in lung tissue." (PMID 33645621, 2021).
Adrenal insufficiency (1 paper, 2023). Insufficient production of steroid hormones (primarily cortisol) by the adrenal glands. "Further, we showed that H2S attenuated hypoxia-induced adrenal insufficiency, which was associated with NLRP3 inflammasome activation and pyropotosis in adrenal gland." (PMID 36661247, 2023). "Mechanically, we demonstrated that H2S S-sulfhydrated PSMA7 at cysteine 70 and subsequently inhibited NLRP3 expression to prevent hypoxia-induced adrenal insufficiency." (PMID 36661247, 2023).
Age-related cataract (1 paper, 2023). A type of cataract (opacification of the lens) that forms during the course of aging. "Studies have found that pyroptosis has a role in the development of age-related cataracts, and inhibitors of the pyroptosis-related NLRP3 factor can effectively inhibit the disease's occurrence." (PMID 37418795, 2023).
Ageusia (1 paper, 2025). A rare condition that is characterized by a complete loss of taste function of the tongue. "Next, the expression of APE1 was upregulated in symptomatic patients and those with ageusia/anosmia, and its expression positively correlated with NLRP3, although not significantly." (PMID 39810451, 2025).
allergic bronchopulmonary aspergillosis (1 paper, 2021). Allergic bronchopulmonary aspergillosis (ABPA) is a rare immunologic pulmonary disorder caused by hypersensitivity to Aspergillus fumigatus, clinically manifesting with poorly controlled asthma and recurrent pulmonary infiltrates. "Studies showed that the expression of NLRP3 was increased in lung tissue from patients with allergic bronchopulmonary aspergillosis (ABPA)." (PMID 34222495, 2021).
alopecia (1 paper, 2020). Hair loss usually from the scalp. "Twenty‐four‐month‐old WT animals displayed increased age‐related alopecia than their coveal NLRP3 knockout mice." (PMID 31625260, 2020).
alveolitis (1 paper, 2026). "At day 14, Nlrp3 deficiency reduced persistent Siglec-F+ neutrophils and broadly reduced airway inflammatory cytokines, accompanied by decreased lung damage, alveolitis, collagen deposition, fibrotic nodule expansion, and α-SMA expression, independent of detectable TGFβ changes." (PMID 42071212, 2026).
Aortic dissection (1 paper, 2022). Aortic dissection refers to a tear in the intimal layer of the aorta causing a separation between the intima and the medial layers of the aorta. "The Nlrp3-caspase 1 complex is activated in the condition of aortic dissection and participates in the process of aortic damage by degrading smooth muscle cell contractile protein, promoting macrophage inflammation and MMP9 expression and intensifying extracellular matrix degradation." (PMID 35211530, 2022).
Aortic Rupture (1 paper, 2022). The tearing or bursting of the wall along any portion of the AORTA, such as thoracic or abdominal. "In all of them, targeting of the NOD-, LRR- and pyrin domain-containing protein 3 (NLRP3) inflammasome effectively reduced the incidence of aortic disease and aortic rupture, and additionally reduced destruction of the aortic wall." (PMID 35127865, 2022).
aortic valve calcification (1 paper, 2024). "While IFN-γ promoted aortic valve calcification and dysfunction, it significantly decreased NLRP3 signaling in splenic macrophages and Ly6C+ monocytes." (PMID 39080527, 2024).
aortic valve stenosis (1 paper, 2025). Aortic valve stenosis (AVS) is a condition characterized by narrowing of the heart's aortic valve opening. "CY-09 exerted a protective effect on calcified aortic valve stenosis in addition to blocking NLRP3 with CAPE." (PMID 40079000, 2025). "Blocking the NLRP3 inflammasome also reduces osteogenic calcification and macrophage polarization in a mouse model of calcified aortic valve stenosis." (PMID 40079000, 2025).
Ascites (1 paper, 2022). Accumulation of fluid in the peritoneal cavity (between the layers of the peritoneum that lines the abdomen). "What is more, this research also found that ADA and NLRP3 were directly proportional to the disappearance time of abdominal pain and ascites in TP patients, suggesting that the increased levels are directly related to the pathological manifestations of patients." (PMID 36157218, 2022). "In addition, ADA and NLRP3 in RG patients were positively correlated with the disappearance time of abdominal pain and ascites (P < 0.05) and had excellent predictive effect on the adverse reactions during treatment (P < 0.05)." (PMID 36157218, 2022). "After treatment, ADA and NLRP3 of ascites in RG were lower than those before treatment (P < 0.05)." (PMID 36157218, 2022).
astrocytomas (1 paper, 2021). "In fact, significant upregulations of MYD88, SRF, JUN, IL1B, TRIF, RIPK1, NLRP3 were detected in GBM cases compared to lower grade astrocytomas (AGII and AGIII)." (PMID 33446690, 2021). "Our transcriptomic data of U87MG cells 12 h after LPS stimulation and the TCGA RNASeq dataset of astrocytoma showed upregulation of genes related to inflammasome and ripoptosome pathways, namely MYD88, NLRP3, RIPK1 and RIPK3, and also SRF, JUN and IL1B, the downstream regulated genes." (PMID 33446690, 2021).
Barrett esophagus (1 paper, 2025). Esophageal lesion lined with columnar metaplastic epithelium which is flat or villiform. "Furthermore, studies have reported the activation of the NLRP3 inflammasome in Barrett's esophagus cells, and activation of the NLRP3 inflammasome has also been observed in esophageal epithelial cells stimulated by acidic bile salts." (PMID 40360974, 2025).
bladder tumor (1 paper, 2022). "Furthermore, the mechanism of monoclonal polysaccharide was investigated, and it was found that the TLR2/NF-κB/NLRP3 pathway promoted the polarization of TAM cells toward M1 and secreted pro-inflammatory factors to improve the bladder tumor microenvironment." (PMID 35603205, 2022).
blood pressure (1 paper, 2021). "High blood pressure triggers the NOD-like receptor (NLR) family pyrin domain containing 3 (NLRP3) inflammasome in cardiomyocytes through calcium/calmodulin-dependent protein kinase II-delta (CaMKIId) activation." (PMID 34884857, 2021).
bronchiectasis (1 paper, 2025). Segmental, irreversible dilation of the bronchial tree resulting in the accumulation of secretions which leads to obstruction. "Collectively, NLRP3 inflammasome activation facilitates NET formation in bronchiectasis, aggravating inflammation and eliciting injury to epithelial cells." (PMID 41395250, 2025). "Our findings, together with prior evidence, suggest that activation of the NLRP3–caspase-1 axis in bronchiectasis neutrophils facilitates phenotypic activation and NET formation, but inflammasome signaling is not indispensable for NET release." (PMID 41395250, 2025). "How NLRP3 inflammasome activation precipitates NET formation in bronchiectasis merits investigation." (PMID 41395250, 2025). "We believe that targeting NLRP3 offers promising translational potential to alleviate chronic inflammation and tissue damage in bronchiectasis patients." (PMID 41395250, 2025). "To assess NLRP3 inflammasome activation, we compared sputum caspase-1 p20 expression between bronchiectasis patients and healthy controls." (PMID 41395250, 2025). "NLRP3, ASC, and the active caspase-1 fragment (p20) were significantly higher in patients with bronchiectasis than in healthy controls (P < 0.05)." (PMID 41395250, 2025). "We isolated neutrophils from bronchiectasis patients and treated them with MCC950 (an NLRP3 inhibitor, 10 μM) or Z-VAD-FMK (a caspase inhibitor, 20 μM), followed by stimulation with LPS and nigericin." (PMID 41395250, 2025). "Here, we investigated how nucleotide-binding oligomerization domain-like receptor protein 3 (NLRP3) inflammasome activation modulates NET formation, epithelial inflammation, and injury in bronchiectasis." (PMID 41395250, 2025). "Therefore, further understanding the effect of NLRP3 inflammasome activation in neutrophil may provide insight into pathology and identify new therapeutic targets for the clinical treatment of neutrophilic inflammatory reactions in bronchiectasis." (PMID 41395250, 2025). "Consistently, immunofluorescence staining confirmed increased NLRP3 and ASC expression in neutrophils during AEs compared with neutrophils from healthy controls (both P < 0.05), indicating up-regulation of key inflammasome components in bronchiectasis." (PMID 41395250, 2025). "We clarified the interplay between neutrophil NLRP3 inflammasome activation and NET formation, testing the hypothesis that NETs could activate airway epithelial inflammasome and further amplify the inflammation in conjunction with PsA LPS in bronchiectasis." (PMID 41395250, 2025).
burn (1 paper, 2020). A traumatic injury involving interruption of tissue cohesiveness that results from exposure to caustic chemicals, extreme heat, extreme cold or excessive radiation. "Based on this result, we speculate that effectively inhibiting the expression of the NLRP3 inflammasome in the early stage of alkali corneal burns can inhibit IL-1β secretion and reduce the inflammatory response." (PMID 32322412, 2020).